ENSG00000285901 (novel transcript)
Gene: Protein-coding gene on chromosome 12 (4,273,762 to 4,405,490, forward strand). Ensembl gene ENSG00000285901.
Genetic constraint (gnomAD): Missense variants: 329 observed, 549.6 expected, observed/expected ratio (o/e) 0.6, 90% interval 0.55 to 0.66. Synonymous variants: 198 observed, 215.45 expected, observed/expected ratio (o/e) 0.92, 90% interval 0.82 to 1.03.